PHF19 (PHD finger protein 19)
Description:
Polycomb group (PcG) protein that specifically binds histone H3 trimethylated at 'Lys-36' (H3K36me3) and recruits the PRC2 complex, thus enhancing PRC2 H3K27me3 methylation activity. Probably involved in the transition from an active state to a repressed state in embryonic stem cells: acts by binding to H3K36me3, a mark for transcriptional activation, and recruiting H3K36me3 histone demethylases RIOX1 or KDM2B, leading to demethylation of H3K36 and recruitment of the PRC2 complex that mediates H3K27me3 methylation, followed by de novo silencing. Recruits the PRC2 complex to CpG islands and contributes to embryonic stem cell self-renewal. Also binds histone H3 dimethylated at 'Lys-36' (H3K36me2). Isoform 1 and isoform 2 inhibit transcription from an HSV-tk promoter.
Synonyms: PCL3; DKFZP727G051; MTF2L1; TDRD19B
Tractability: PROTAC: ubiquitination databases record sites on it.
Gene: Protein-coding gene on chromosome 9 (120,855,651 to 120,894,896, reverse strand). Ensembl gene ENSG00000119403.
Subcellular location: Nucleus
Pathways (Reactome):
Gene expression (Transcription): PRC2 methylates histones and DNA
Gene Ontology:
Molecular function: histone H3K36me3 reader activity; protein binding; chromatin binding; histone H3K4me3 reader activity
Biological process: negative regulation of gene expression, epigenetic; heterochromatin formation; negative regulation of transcription by RNA polymerase II; epigenetic regulation of gene expression; stem cell differentiation; stem cell population maintenance
Cellular component: ESC/E(Z) complex; nucleus; nucleoplasm
Genetic constraint (gnomAD): Loss-of-function variants: 17 observed, 53.9 expected, observed/expected ratio (o/e) 0.32, 90% interval 0.22 to 0.47. The upper end of that interval is the gene's LOEUF score, 0.47, which puts it in group 2 of 6, group 1 being the genes least tolerant of losing a copy. Missense variants: 348 observed, 572.85 expected, observed/expected ratio (o/e) 0.61, 90% interval 0.56 to 0.66. Synonymous variants: 204 observed, 238.04 expected, observed/expected ratio (o/e) 0.86, 90% interval 0.76 to 0.96.
Homologues: Orthologues: chimpanzee PHF19 (100% identical), macaque PHF19 (99% identical), guinea pig PHF19 (97% identical), dog PHF19 (97% identical), rabbit PHF19 (95% identical), pig PHF19 (91% identical), rat Phf19 (89% identical), mouse Phf19 (89% identical), zebrafish phf19 (66% identical), tropical clawed frog psmd5 (66% identical), Drosophila melanogaster Pcl (31% identical). Paralogues in human: MTF2 (44% identical), PHF1 (37% identical).
Diseases named in the same sentence as PHF19 in open-access papers:
PHF19 is named in the same sentence as 54 diseases in open-access papers, as found by Europe PMC text mining. Sharing a sentence is not in itself a finding about the gene and the disease. The quoted sentences say what the papers report.
myeloma (12 papers, 2020 to 2025). "For instance, PHF19 expression is present in all subgroups of multiple myeloma (MM) and is preferentially upregulated in high-risk MM." (PMID 35069553, 2021). "Taking all of this into consideration this data may indicate an association between PHF19 and 1q via TF regulation creating unique molecular subtypes of myeloma cells." (PMID 38755140, 2024). "High expression of PHF19 has been reported to be associated with high-risk disease in myeloma." (PMID 37696786, 2023). "Aberrant expression of PHF19 has been implicated in regulating the pathogenesis and progression of a wide range of cancers, including melanoma, hepatocellular carcinoma, glioma, glioblastoma, multiple myeloma." (PMID 32180719, 2020). "Furthermore, post-challenge analysis identified a novel expression-based risk marker, PHF19, which has recently been found to have an important biological role in multiple myeloma." (PMID 32060406, 2020). "Thus, PBX1 and PHF19 may identify high-risk myeloma subtypes, necessitating more intensive treatment." (PMID 41226583, 2025). "PHF19 expression in myeloma cell lines is greatly reduced by PBX1 silencing, although PBX1 amplification on 1q greatly enhances PHF19 levels." (PMID 41226583, 2025). "PHD finger protein 19 (PHF19) is an epigenetic regulator that has recently seen much interest in the myeloma field due to its relationship with poor patient outcomes." (PMID 38755140, 2024). "MTF2, an ancillary subunit of the polycomb repressive complex 2 (PRC2), is a close functional relative of PHD finger protein 19 (PHF19) which is currently emerging as an important driver of myeloma." (PMID 34876184, 2021). "In order to define the transcriptional program and biological pathways promoted by PHF19, we analyzed the gene expression data from the Multiple Myeloma Research Foundation (MMRF) CoMMpass study of 683 newly diagnosed MM and 35 relapse patients." (PMID 34857028, 2021). "Significantly, we showed that knock down of PHF19 shifts myeloma cell lines into a less proliferative state." (PMID 32060406, 2020). "Furthermore, knockdown of PHF19 has been shown to shift myeloma cells into a less proliferative state." (PMID 35105355, 2022). "Interestingly, this PHF19 high myeloma cell subtype also exhibited high expression of genes involved in cell cycle including HELLS, EZH2, TYMS, ZWINT, and MKI67." (PMID 34857028, 2021). "Consistent with our results, past studies have shown that PHF19 knockdown resulted in the reduction of growth and cell cycle arrest in multiple myeloma, and reduced PHF19 levels in chronic myeloid leukemia cells arrested the cell cycle and promoted differentiation toward erythroid fate." (PMID 35069553, 2021). "In myeloma, PHF19 promotes its tumorigenesis through activating PRC2 complex." (PMID 32180719, 2020). "From the myeloma cell lines MM1S and U266, both of which have Gain/Amp1q, ChIP-seq peaks were identified in the promoter of PHF19 that were in the top 4% of MM1S ChIP-seq peaks and the top 8% of U266 ChIP-seq peaks." (PMID 38755140, 2024). "When myeloma cell lines overexpressed PBX1, we saw the opposite effect of the knockdown of PBX1 on PHF19 expression." (PMID 38755140, 2024). "For example, in the blood cancer multiple myeloma, MTF2 and PHF19 were found to be upregulated compared to plasma cells from healthy individuals and were associated with high-risk disease." (PMID 37895228, 2023). "For example, PHD Finger Protein 19 (PHF19) contributes to cardiac hypertrophy and multiple myeloma." (PMID 41268576, 2025). "Further investigation is needed to unravel the oncogenic networks involving MTF2, PHF19, and WDR26 in myeloma, as this could reveal novel opportunities for targeted molecular treatments and prevention strategies." (PMID 37895228, 2023).
hepatocellular carcinoma (10 papers, 2017 to 2024). A malignant tumor that arises from hepatocytes. "At a post-transcriptional level, PHF19 expression was shown to be regulated by several MicroRNA (miRNA) including miR-211 (in ovarian carcinoma), miR-497 and miR-195-5p (in hepatocellular carcinoma), miR-15a (in gastric cancer and MM)." (PMID 34857028, 2021). "This gene inhibits hepatocellular carcinoma by regulating PHF19, regulates rectal cancer through CDK8, regulates osteosarcoma by inhibiting NKD1, regulates prostate cancer through Fra-1 or RPS6KB1." (PMID 28498798, 2017). "Moreover, PHF14 and PHF19 are identified as key players in glioblastoma, colorectal, and hepatocellular cancers, influencing crucial pathways such as Wnt, AKT, ERK1/2, and Hedgehog-Gli1." (PMID 38813086, 2024). "PHD finger proteins, particularly PHF14 and PHF19, exhibit a profound capacity to regulate immune cell infiltration and checkpoint gene expression within tumors, thereby influencing the immune landscape of various cancers, including hepatocellular carcinoma." (PMID 38813086, 2024). "Finally, due to the fact that functional enrichment analysis of PHF19 was obviously correlated with hepatocellular carcinoma (HCC), we constructed a PHF19-related prognostic risk-score model for HCC patients and performed a validation of this model in an external dataset." (PMID 35069553, 2021). "In addition, PHF19 can promote proliferation in hepatocellular carcinoma, glioma, and ovarian cancers and can induce glioblastoma progression, mediated by β-catenin." (PMID 32155117, 2020). "However, contradictory findings have also been reported, showing a positive role of PHF19 promoting migration and invasion in hepatocellular carcinoma and glioblastoma cells." (PMID 32155117, 2020). "A study in hepatocellular carcinoma (HCC) suggests that a high expression of PHF19 promotes cell migration and invasiveness but also proliferation." (PMID 37107696, 2023). "In hepatocellular carcinoma (HCC) progression, PHF19 influences the Hedgehog-Gli1 signaling pathway." (PMID 38813086, 2024). "Based on these findings, a potential miR-497-mRNA or miR-1246-mRNA regulatory network can be established, namely, miR-497-ARL2/UBE2Q1/PHF19/APLN/CHEK1/CASK/SUCO/CCNE1/KIF23, or miR-1246-AUTS2/SLAIN1, which contributes to the occurrence and development of hepatocellular carcinoma." (PMID 34163524, 2021). "Finally, a recent study showed that the short isoform of PHD finger protein 19 (PHF19) interacts with β-TRCP to inhibit Gli1 ubiquitination and thus promoting Hh signaling in hepatocellular carcinoma (HCC)." (PMID 34948134, 2021). "Regarding the short isoform of hPCL3/PHF19, hPCL3S, it has been shown to be up-regulated in hepatocellular carcinomas (HCC) clinical samples and to promote the growth and migration of HCC in vitro as well as their metastasis in vivo using mouse xenografts models." (PMID 32256978, 2020).
glioblastoma (9 papers, 2018 to 2021). The most malignant astrocytic tumor (WHO grade IV). "In liver cancer, glioblastoma, multiple myeloma, gastric cancer, and melanoma, PHF19 has been confirmed to be highly expressed and was closely related to the prognosis of patients." (PMID 34141488, 2021). "Previous studies have found a positive correlation between PHF19 expression and glioblastoma progression." (PMID 34078310, 2021). "Among different tumors, PHF19 was found to be significantly up-regulated in tumor tissues, which is considered to be closely related to the poor prognosis of patients, such as gastric cancer, melanoma, liver cancer, glioblastoma." (PMID 34141488, 2021). "For instance, PHF19 activates β-catenin signaling in glioblastoma to confer doxorubicin resistance." (PMID 31501414, 2019). "However, the biological functions and molecular mechanisms of PHF19 in glioblastoma (GBM) remain unclear." (PMID 30323224, 2018). "Significantly elevated in the advanced stages of Glioblastoma (GBM), PHF19 was reported to block the degradation of β-catenin via transcriptional repression of SIAH1 and promote the progression of GBM." (PMID 35069553, 2021).
glioma (8 papers, 2013 to 2021). A benign or malignant brain and spinal cord tumor that arises from glial cells (astrocytes, oligodendrocytes, ependymal cells). "Moreover, Kaplan–Meier analysis demonstrated that PHF19 expression levels were positively associated with glioma grade." (PMID 30323224, 2018). "PHF19 increases the expression of β-catenin, N-cadherin, Snail and other molecules in gliomas, inhibits the expression of E-cadherin, and promotes the occurrence of metastatic malignant phenotypes of gliomas." (PMID 34141488, 2021). "The results showed that PHF19 expression levels were significantly increased in the advanced stages of glioma compared to those in adjacent normal tissues." (PMID 30323224, 2018). "Similarly, PHF19 has been found to be upregulated in human glioma cells and can drive the proliferation of glioma cells." (PMID 31798343, 2019). "To determine whether the PHF19 is a prognostic factor for poor survival, we performed immunohistochemical staining on primary tissue microarray samples from glioma patients." (PMID 30323224, 2018). "PHF19 could form the PRC2 with Ezh2, EED, and SUZ12, knockdown of the PHF19 gene suppressed Ezh2 phosphorylation and proliferation in glioma cells." (PMID 35003347, 2021). "However, in a cohort which includes low grade gliomas, significant survival benefits were observed for patients with low EZH2, PHF19, CBX8 and PHC2 expression, and high CBX7, CBX6, RYBP and EZH1 expression." (PMID 24260522, 2013).
melanoma (8 papers, 2020 to 2023). A malignant, usually aggressive tumor composed of atypical, neoplastic melanocytes. "In melanoma, Akt has been found to play a biological effect as an upstream regulatory molecule of PHF19." (PMID 34141488, 2021). "PHF19 has also been deemed to play a role in the switch from proliferative to invasive states in melanoma cells." (PMID 33800594, 2021). "For instance, PHF19 knockdown reduces the cell proliferation rate and increases the migration capacities of melanoma cells." (PMID 32180719, 2020). "In melanoma cell lines, pharmacological AKT inhibition leads to decreased expression of PHF19 protein." (PMID 34857028, 2021). "Using immunofluorescence and ChIP-qPCR it has been shown that pAKT is present in the nucleus of the human melanoma cell line HT144 and that it localizes to the promotor of PHF19." (PMID 34857028, 2021). "The first functional study in cancer about PHF19 was performed in melanoma cells, where depletion of PHF19 leads to reduced proliferation but enhances invasiveness, suggesting a nontrivial role of PHF19." (PMID 37107696, 2023). "In contrast, PHF19 is not reported in phagocytosis but has vastly been reported in cancer research, most prominently in malignant melanoma." (PMID 35651604, 2022). "Interestingly, the absence of PHF19 changes the properties of the cells to a less proliferative but, at the same time to a more aggressive phenotype, similar to the effect in melanomas." (PMID 37107696, 2023).
colorectal cancer (7 papers, 2017 to 2025). A primary or metastatic malignant neoplasm that affects the colon or rectum. "Further studies should aim to investigate the functional relevance of the PHF19-207 transcript in colorectal cancer." (PMID 40723829, 2025). "The role of PHF19 protein in malignant transformation has been demonstrated in several malignancies, with its tumor-promoting role in colorectal cancer revealed only recently." (PMID 40723829, 2025). "Via motif and core regulatory circuitry analysis, multiple important transcription factors in colorectal cancer were predicted, with PHF19, TBC1D16 and KLF3 having a special role to play in colorectal cancer carcinogenesis." (PMID 38542080, 2024). "Tissue microarray analysis of surgically resected paired colorectal cancer (CRC) samples showed that PHF19 protein was overexpressed in CRC tissues compared with paired adjacent normal tissues." (PMID 35069553, 2021). "The objective of our study was to examine the expression of PHF19-207 in colon cancer, assess its potential as an early biomarker for colorectal cancer, and evaluate its functional implications using in silico tools, as the function of this transcript has not been previously characterised." (PMID 40723829, 2025). "Considering the increasing incidence of colorectal cancer in younger populations and the need for improved early detection, PHF19-207 expression could be explored as the basis for a relatively simple and efficient test, enabling a more comprehensive and affordable screening strategy." (PMID 40563408, 2025). "Further experiments verify the function of the super enhancers governing PHF19 and TBC1D16 in regulating colorectal cancer tumorigenesis, and KLF3 is identified as an oncogenic transcription factor in colorectal cancer." (PMID 34737287, 2021). "The upregulation of PHF19 (3 fold increase) which codes for PHD (Cys4-His-Cys motif) finger protein 19, a histone binding protein with embryonic stem cell self-renewal function, suggests it may have oncogenic function in colorectal cancer." (PMID 29088818, 2017).
ovarian carcinoma (6 papers, 2020 to 2023). A malignant neoplasm originating from the surface ovarian epithelium. "Gain of function and loss of function experiments further proved that PHF19 is a crucial mediator involved in the ovarian cancer progression, including cell proliferation, invasion, migration, and stemness." (PMID 32180719, 2020). "A similar link between an miRNA and a PHF19 has been proposed in ovarian carcinoma, where PHF19 expression is regulated by miR-211." (PMID 37107696, 2023). "PHF19 silencing reduced the proliferation, and induced apoptosis and cell cycle stagnation in ovarian cancer cells." (PMID 34078310, 2021). "Yet in certain studies, PHF19 expression was lower in bladder cancer, breast cancer, leukemia, ovarian cancer, and prostate cancer." (PMID 35069553, 2021). "To further understand the reason why PHF19 enhances the resistance of ovarian cancer cells to CFG, we attempted to performed the following rescue experiments." (PMID 32180719, 2020). "More importantly, the present study is the first to report that PHF19 enhances tumor stemness in ovarian cancers." (PMID 32180719, 2020). "In the present study, we found that the resistance ability of ovarian cancer cells to CFG positively correlated with PHF19 expression, which promoted us to determine the response of ovarian cancer cells with PFH19 overexpression or knockdown to CFG." (PMID 32180719, 2020). "In the present study, we found that PHF19 expression in ovarian cancer cells positively correlated with their resistance ability to CFG." (PMID 32180719, 2020). "Overall, our results provide a series of evidence to reveal that PHF19 is critical suppressor for CFG’s anti-tumor effect in ovarian cancer." (PMID 32180719, 2020). "In order to further confirm the role of PHF19 in ovarian cancer cell progression, the cell invasion and migration capacities were determined in HEY-T30 and SKOV3 cells with/without PHF19 overexpression or knockdown by Transwell assays." (PMID 32180719, 2020). "We have previously found that miR-211 can suppress the expression of PHF19 in ovarian cancer cells by targeting to its 3’ untranslated region (3’ UTR)." (PMID 32180719, 2020). "Taken together, our findings provide systematic evidence that PHF19 serves as an important suppressor for the anti-tumor effect of CFG in ovarian cancer." (PMID 32180719, 2020). "In conclusion, results of the current study demonstrate that CFG exerts its anti-tumor function in ovarian cancer, at least partially, depending on the downregulation of PHF19." (PMID 32180719, 2020). "Next, we further evaluated the effect of CFG on ovarian cancer SKOV3 cells with PHF19 knockdown, including cell apoptosis, invasion, migration and stemness." (PMID 32180719, 2020). "In this study, we further elucidate the exact role of PHF19 in ovarian cancer proliferation, apoptosis, invasion, and migration by a series of gain-of-function and loss-of-function experiments both in HEY-T30 and SKOV3 cells." (PMID 32180719, 2020). "Moreover, rescue the expression of PHF19 reverted CFG-induced suppression in the cell growth, EMT and stemness of ovarian cancer cells, while knockdown of PHF19 accelerated the anti-tumor effect of CFG." (PMID 32180719, 2020). "Therefore, it can be concluded that PHF19 antagonizes CFG’s anti-tumor effect in ovarian cancer by protecting cell proliferation, invasion, migration, and stemness." (PMID 32180719, 2020). "The expression profiles and function of the shorter isoform of PHF19 in ovarian cancer are still unknown." (PMID 32180719, 2020). "In this study, before elucidating the mechanisms of PHF19 underlying the resistance of ovarian cancer cells to CFG, we systematically determine the function of PHF19 in the pathogenesis of ovarian cancer by conducting gain-of-function and lose-of-function experiments." (PMID 32180719, 2020).